HPSE (heparanase)
Diseases named in the same sentence as HPSE in open-access papers (continued):
Sharing a sentence is not in itself a finding about the gene and the disease.
gastric cancer (30 papers, 2010 to 2025). A primary or metastatic malignant neoplasm involving the stomach. "Studies on chronic gastritis induced by Helicobacter pylori (considered the major risk factor for gastric cancer) have suggested that HPSE is upregulated and is involved in the early stages of gastric cancer." (PMID 41301515, 2025). "In a study showing that RSV decreases NF-κB transcriptional activity in an experimental model, they analyzed changes in heparanase activity, which was linked to NF-κB expression in gastric cancer cells after RSV treatment." (PMID 39795061, 2024). "NF-κB activation has been linked to the increased expression of heparanase during the invasion of gastric cancer cells." (PMID 35630523, 2022). "A meta-analysis with a total of 27 studies which included 3891 gastric cancer patients showed that higher heparanase expression in gastric cancer is associated with clinicopathologic features of depth of invasion, lymph node metastasis, and TNM stage." (PMID 32121387, 2020). "Our findings reveal the mechanisms of HPSE gene expression associated with gastric cancer progression, and suggest that miR-558 and Smad4 are potential therapeutic targets of gastric cancer." (PMID 27685626, 2016). "In conclusion, this study evaluated polymorphisms of the HPSE gene in gastric cancer with a MALDI-TOF MS method and archived FFPETs in a large northern Chinese case-controlled cohort." (PMID 22276173, 2012). "The present study examined the associations between individual SNPs or haplotypes in HPSE and susceptibility, clinicopathological parameters and prognosis of gastric cancer in a large sample of the Han population in northern China." (PMID 22276173, 2012). "Moreover, human telomerase reverse transcriptase (hTERT), which sustains telomere length in many cancers, has been linked to Myc- and HPSE-driven signaling in gastric cancer." (PMID 41301515, 2025). "Similarly, H. pylori-induced gastric inflammation and the associated up-regulation of heparanase, observed in the current study, likely promote the development of gastric cancer." (PMID 34220822, 2021). "Inhibition of heparanase by heparin/HS mimicking compounds, neutralizing antibodies and/or small molecules may block this self-sustaining pro-inflammatory cycle and thereby reduce the risk of gastritis and the associated gastric cancer." (PMID 34220822, 2021). "The reduction in heparanase activity correlates with decreased NF-kB transcriptional activity and attenuates the invasion potential in gastric cancer cells." (PMID 38999888, 2024). "Zheng et al37 showed that endogenous miR‐558 decreased the binding of Smad4 to HPSE, activated the transcription and expression of HPSE, and promoted tumorigenesis and invasion of gastric cancer cells both in vitro and in vivo." (PMID 37563869, 2023). "Our data indicate for the first time that RSV significantly decreases the heparanase activity in gastric cancer cell lines AGS and MKN45." (PMID 35630523, 2022). "So, miR-1258 acted as a tumor suppressor to inhibit invasion and metastasis by targeting HPSE (heparanase) in gastric cancer and inhibited growth and EMT via targeting SP1 in oral squamous cell carcinoma." (PMID 35163224, 2022). "In this regard, our results showed that RSV reduces heparanase activity in the gastric cancer cells used in this study." (PMID 35630523, 2022). "Heparanase is a critical effector during the metastasis process in gastric cancer development by promoting the invasion of malignant cells to distant organs." (PMID 35630523, 2022). "On the other hand, it was reported that NF-κB partially regulated the expression of HPSE in the gastric cancer cell line MKN74." (PMID 35630523, 2022). "Accordingly, heparanase inhibition was correlated with the increased activity of SOD in gastric cancer cells treated with RSV." (PMID 35630523, 2022).
gastric cancer (continued). "In summary, these results show that RSV increases SOD activity but decreases NF-kB transcriptional activity and heparanase enzymatic activity, which correlates with the attenuation of invasion potential in gastric cancer cells." (PMID 35630523, 2022). "Our results suggest that heparanase is a relevant effector during the invasion of gastric cancer cells and that its activity would be affected by the effect of RSV on SOD and NF-κB activities." (PMID 35630523, 2022). "Since heparanase is a critical effector during the metastasis process in gastric cancer development, these results provide valuable information for designing effective therapies based on the use of RSV." (PMID 35630523, 2022). "In this research, we demonstrate that the HPSE expression is obviously increased in bladder, breast, lung, and stomach cancer, but decreased in colon, head, and neck cancer." (PMID 34461608, 2021). "On the other hand, high miR-558 levels induce HPSE expression in gastric cancer cells and neuroblastoma by targeting the HPSE promoter and thus facilitating tumor progression." (PMID 33809973, 2021). "It has been previously reported that heparanase induced by H. pylori infection facilitates the proliferation, invasion and metastasis of gastric cancer cells." (PMID 34220822, 2021). "HPSE expression was significantly increased in bladder, breast, lung, and stomach cancer compared to matched normal tissues." (PMID 34461608, 2021). "The gut pathogen Helicobacter pylori (H. pylori) also induced heparanase expression in gastric cancer cells and this was found to be dependent on MAPK signaling." (PMID 34681753, 2021). "Hepatocyte growth factor (HGF) has also been shown to upregulate heparanase expression at the transcriptional level in lung and gastric cancer cells." (PMID 34681753, 2021). "This confirms previous reports that connect the p38 MAPK pathway with heparanase expression in gastric cancer cells." (PMID 34220822, 2021). "Comparison of Oncomine and Timer results indicated that the HPSE expression was significantly increased in bladder, breast, lung, and stomach cancer, while it was decreased in colon, head, and neck cancer." (PMID 34461608, 2021). "For example, a meta-analysis of 27 studies confirmed that HPSE expression was correlated with clinicopathological features in gastric cancer patients." (PMID 28388549, 2017). "hTERT can also act as a coactivator of c-Myc to induce the expression of heparanase, which in turn enhances the invasion and metastasis of gastric cancer cells." (PMID 28291810, 2017). "Knockdown of AGO1, but not of Argonaute 2 (AGO2), Argonaute 3 (AGO3) or Argonaute 4 (AGO4), abolished the miR-558-facilitated protein and transcriptional levels of HPSE in gastric cancer cells." (PMID 27685626, 2016). "Previous studies have indicated that as the only mammalian endo-β-D-glucuronidase, heparanase (HPSE) is up-regulated and associated with poor prognosis in gastric cancer, while the underlying mechanisms still remain to be determined." (PMID 27685626, 2016). "Meanwhile, knockdown or over-expression of HPSE prevented the gastric cancer cells from alteration in the growth, invasion and angiogenesis induced by ectopic expression of miR-558 or Smad4, respectively." (PMID 27685626, 2016). "To investigate the regulators crucial for the expression of HPSE in gastric cancer, we analysed the potential binding sites of transcription factor within its promoter, using computational algorithm programmes." (PMID 27685626, 2016). "Since AGO1 is important for active chromatin remodelling at gene promoters induced by miRNA,41 we further observed the functions of AGO1 in miR-558-activated expression of HPSE in gastric cancer." (PMID 27685626, 2016). "Similar results have been described, suggesting that higher heparanase expression in gastric cancer tissues was closely correlated with lower treatment responsiveness and poor prognosis." (PMID 25351637, 2015).
gastric cancer (continued). "It has been proved that RNAi-induced heparanase silencing can inhibit cell invasion of gastric carcinoma, hepatocellular carcinoma and embryonal rhabdomyosarcoma." (PMID 25185798, 2014). "The present results demonstrated our presumption that SNPs were involved in the regulation of heparanase expression, thereby affecting invasion ability and survival in gastric cancer." (PMID 22276173, 2012). "Three heparanase-specific small interfering RNA (siRNAs) were designed, synthesized, and transfected into cultured gastric cancer cell line SGC-7901." (PMID 20137078, 2010). "In addition, new evidence has indicated that both active and inactive HPSE modulate TFEB-mediated autophagy in gastric cancer cells." (PMID 41301515, 2025). "Heparanase activity was reduced in AGS cells treated with 5–25 μM RSV, so it can be concluded that resveratrol reduces heparanase activity in gastric cancer cells, which correlates with increased SOD activity and the inhibition of NF-κB transcriptional activity." (PMID 39795061, 2024). "In addition, a positive correlation between c-myc and heparanase-1 was observed in gastric cancer through the indirect upregulation of heparanase-1 via the activation of human telomerase reverse transcriptase (hTERT)." (PMID 36680276, 2023). "This article proposes that heparanase could be a key effector in the invasive events occurring during gastric cancer metastasis." (PMID 35630523, 2022). "Importantly, this study provides the first evidence that RSV treatment significantly reduces the heparanase activity in gastric cancer cells." (PMID 35630523, 2022). "Furthermore, a recent study revealed that heparanase enhances gastric cancer progression independently of its enzymatic activity by triggering the transcription factor EB (TFEB)-driven autophagy, in addition to the associated cell proliferation." (PMID 36293542, 2022). "Furthermore, in a clinical cohort of gastric cancer patients with H. pylori infection, heparanase expression correlated with poor overall survival and relapse-free survival." (PMID 34681753, 2021). "Moreover, miR-429 exhibits a reduced expression in gastric cancer tissues and its overexpression inhibits the transcription and translation of the HPSE gene, decreasing their invasive properties." (PMID 33809973, 2021). "However, the role of heparanase in gastritis and the early stages of gastric cancer initiation is still obscure." (PMID 34220822, 2021). "Additionally, the activation of the PI3K/Akt pathway by HGF signalling was shown to stimulate the downstream expression of HPSE, promoting gastric cancer metastasis." (PMID 33256730, 2020). "Although a relationship similar to that between Ras and HPSE has not been reported for Myc, human telomerase reverse transcriptase (hTERT), which plays a pivotal role in maintaining telomere length in many cancers, was shown to correlate with Myc and HPSE expression in gastric cancer." (PMID 33256730, 2020). "Moreover, ectopic expression or knockdown of miR-558 led to increase and decrease in the nascent transcription and transcript levels of HPSE in gastric cancer cell lines, respectively." (PMID 27685626, 2016). "Notably, the expression levels of Smad4 or miR-558 were inversely (R=−0.663, P<0.001) and positively (R=0.817, P<0.001) correlated with those of HPSE in gastric cancer tissues, respectively." (PMID 27685626, 2016). "Human heparanase plays an important role in cancer development and single nucleotide polymorphisms (SNPs) in the heparanase gene (HPSE) have been shown to be correlated with gastric cancer." (PMID 22276173, 2012). "SNPs in HPSE play an important role in gastric cancer progression and survival, and perhaps may be a molecular marker for prognosis and treatment values." (PMID 22276173, 2012). "Our studies indicated that heparanase was frequently expressed in advanced gastric cancers." (PMID 20137078, 2010).
gastric cancer (continued). "The aim of this study is to determine whether silencing of heparanase expression can abolish the malignant characteristics of gastric cancer cells." (PMID 20137078, 2010). "Additionally, it was reported that the nuclear accumulation of NF-κB subunits correlated with increased heparanase expression and poor clinicopathological features of gastric cancer specimens, suggesting an important role for NF-κB signaling in the gastric metastatic process." (PMID 35630523, 2022). "Similarly, miR-429 reduced gastric cancer cell invasiveness by repressing heparanase expression." (PMID 33714199, 2021). "Hence, Heparanase could have a promoting role in gastric cancer spread, and therefore SATB1 could be associated with gastric cancer dissemination." (PMID 31450715, 2019). "Furthermore, miR-558 is up-regulated in gastric cancer, and promotes the transcription of HPSE via abolishing the binding of Smad4 to its promoter, resulting in increased in vitro and in vivo growth, invasion, metastasis and angiogenesis of gastric cancer cells." (PMID 27685626, 2016). "Moreover, high expression of heparanase is frequently observed in an increasing number of primary human tumors, such as prostate cancer, bladder cancer and gastric cancer, and the heparanase-facilitated invasion and metastasis induce poor outcomes in cancer patients." (PMID 22363633, 2012). "Similarly, in colorectal cancer, the role of HPSE is mainly associated with the recruitment of macrophages, generating a vicious cycle (driven by the NF-kB and p38-MAPK signaling pathways) that sustains chronic inflammation, supporting the development and progression of gastric cancer." (PMID 41301515, 2025). "Moreover, the treatment of other gastric cancer cell lines, AGS and MKN45, with resveratrol results in reduced heparanase activity alongside increased superoxide dismutase activity, an antioxidant enzyme." (PMID 38999888, 2024). "Additionally, heparanase expression is positively related to advanced tumor stages (TNM classification), invasion depth, and poor prognosis in gastric cancer." (PMID 35630523, 2022). "Considering these antecedents, we hypothesize that RSV might affect the invasive potential of gastric cancer cells by modulating NF-κB, SOD, and heparanase activity." (PMID 35630523, 2022). "It remains to be elucidated whether the currently observed H. pylori-heparanase axis involves WDR5 induction and H3K4 methylation, given their important epigenetic roles in the progression of various cancers including gastric cancer." (PMID 34220822, 2021).
hepatocellular carcinoma (29 papers, 2008 to 2025). A malignant tumor that arises from hepatocytes. "The expression of heparanase (HPSE) was associated with postoperative metastatic recurrence in patients with hepatocellular carcinoma (HCC)." (PMID 25149140, 2014). "The overexpression of heparanase-1 correlates with pathological scenarios and is observed in different human malignancies, such as lymphoma, breast, colon, lung, and hepatocellular carcinomas." (PMID 36680276, 2023). "Alterations in HS and elevated levels of heparanase expression have been found in diseased liver, correlated with the degree of liver fibrosis and hepatocellular cancer, implying that heparanase plays a role in the pathogenesis of liver diseases." (PMID 35805119, 2022). "In the current study, we investigated whether HPSE SNPs were a hepatocellular carcinoma (HCC) risk factor by carrying out a comprehensive case-control pilot study." (PMID 33411145, 2021). "Heparanase plays a proadhesive role in cell adhesion and tumor microembolus in hepatocellular carcinoma." (PMID 32471161, 2020). "Recently, a small molecule inhibitor of heparanase was shown to reduce metastatic characteristics in a hepatocellular carcinoma model." (PMID 32471161, 2020). "Heparanase expression (RT-PCR) and enzymatic activity were examined in various hepatocellular carcinoma (human HepG2, Hep3B) and lung carcinoma (human HCC827, mouse LLC) cell lines." (PMID 28359266, 2017). "We first overexpressed heparanase in three hepatoma cells lines and found a significant suppression of hepcidin expression in all of them." (PMID 27711215, 2016). "TGS can effectively interfere with the heparanase gene to reduce the invasion and migration of hepatoma SMCC-7721 cells." (PMID 25185798, 2014). "This study investigated the effect of transcriptional gene silencing (TGS) of the heparanase gene on hepatoma SMCC-7721 cells." (PMID 25185798, 2014). "The aim of this study was to investigate the antimetastatic effect of multiple antigenic polypeptide (MAP) vaccine based on B-cell epitopes of heparanase (HPSE) on human hepatocellular carcinoma (HCC) in vivo." (PMID 23308126, 2013). "Because heparanase enzymatically cleaves HS glycosaminoglycan chains from proteoglycans to release the active form of bFGF from the ECM, we attempted to assess the level of heparanase in the hepatoma cells after treatment with fucoidan." (PMID 23737842, 2013). "The downregulation of the expression of heparanase inhibits the angiogenesis induced by hepatocellular carcinoma (HCC) cells both in vitro and in vivo." (PMID 23737842, 2013). "The role of heparanase (HPSE) gene in cancers including hepatocellular carcinoma (HCC) is currently controversial." (PMID 22952874, 2012). "Inthis study, we investigated whether SNPs in HPSE were a riskfactor for hepatocellular carcinoma (HCC) by undertaking a comprehensivehaplotype-tagging, case-control study." (PMID 28981558, 2017). "Invasion and wound healing assays showed that both TGS and PTGS of the heparanase gene could inhibit invasion and migration of hepatoma SMCC-7721 cells, especially the TGS group." (PMID 25185798, 2014). "We found that TGS could effectively interfere with the heparanase gene to reduce the invasion and migration of hepatoma SMCC-7721 cells, which is a very important experimental basis for TGS research in cancer gene therapy." (PMID 25185798, 2014). "In addition, wound healing and invasion assays were performed to estimate the effect of TGS of the heparanase gene on the migration and invasion of hepatoma SMCC-7721 cells." (PMID 25185798, 2014). "In combination, these results suggest that both TGS and PTGS of heparanase gene could inhibit the migration of hepatoma SMCC-7721 cells." (PMID 25185798, 2014). "Heparanase (HPSE) is a kind of multifunctional extracellular hydrolase, and related to metastasis of hepatocellular carcinoma (HCC)." (PMID 33597510, 2021).
hepatocellular carcinoma (continued). "The clinical utility of a mixture of sulfated oligosaccharides (PI-88) with dual heparanase and angiogenic inhibitory activity has been previously demonstrated in a phase II clinical trial for hepatocellular carcinoma (HCC)." (PMID 21285983, 2011). "Prior studies have demonstrated that TGF-β signaling in hepatocellular carcinoma induces MMP-7 and heparanase, promoting syndecan-1 shedding and enhancing fibrogenic signaling." (PMID 40572724, 2025). "As the most advanced heparanase inhibitor, it is currently being trialed in a Phase III study as an adjuvant treatment for patients with hepatitis virus related hepatocellular carcinoma after surgical resection." (PMID 25105093, 2014). "The heparanase expression of both TGS and PTGS transfected hepatoma SMCC-7721 cells had recovered at 96 h post-transfection." (PMID 25185798, 2014). "In the present study, siRNA was transfected into hepatoma SMCC-7721 cells using TGS and PTGS to interfere with the expression of heparanase." (PMID 25185798, 2014). "As with gene expression, the heparanase protein levels of both TGS and PTGS transfected hepatoma SMCC-7721 cells had recovered at 96 h post-transfection." (PMID 25185798, 2014). "Given the overexpression of heparanase in hepatocellular and lung carcinoma cancer cell lines, we next analyzed the effect of triazolo-thiadiazoles on LLC (Lewis Lung carcinoma) and HepG2 (hepatocellular carcinoma) cell proliferation using the MTT assay." (PMID 28359266, 2017). "It has been reported that HPSE expression is notably reduced in hepatocellular carcinoma (HCC) tissues compared with non-tumor liver tissues and is significantly associated with poor outcomes." (PMID 35840985, 2022).